KRAS (KRas proto-oncogene, GTPase)
Diseases named in the same sentence as KRAS in open-access papers (continued):
Sharing a sentence is not in itself a finding about the gene and the disease.
cancer (continued). "Mutations that change the gene encoding a protein called KRAS are found in many different types of cancer." (PMID 24623306, 2014). "Constitutive, signal-independent activation of KRAS via mutation is not only associated with poor prognosis and therapy resistance in a variety of cancers, but is sufficient to trigger malignant transformation and drive the oncogenic phenotype." (PMID 24955217, 2014). "For example, G12V mutations are ten times more abundant than G12D mutations in HRAS cancer samples, whereas for KRAS and NRAS G12D mutations predominate." (PMID 25109951, 2014). "KRAS mutations were present in 28% BRAFwt/MSS cancers and the mutual exclusivity of KRAS with BRAF mutations was confirmed." (PMID 24651849, 2014). "This example makes use of the KRAS gene, a gene that is commonly mutated and constitutively active in many cancer types, leading the cell to replicate DNA and make copies of itself at a very fast pace." (PMID 25937882, 2014). "Activating mutations in the KRAS gene are important drivers of carcinogenesis in many types of cancer, such as lung, colon and pancreas." (PMID 24368337, 2014). "By combining the copious amount of sequencing data over the past year, we find that the PIK3CA gene is one of the two most commonly mutated genes identified in human cancers (the other being KRAS)." (PMID 25106743, 2014). "MEK inhibitors in patients with KRAS-mutated advanced cancer were associated with higher clinical benefit rates compared to other therapies." (PMID 25313136, 2014). "A single amino acid substitution in KRAS results in activating mutation and dependence of the cancer cells on the MAP kinase pathway." (PMID 24874471, 2014). "In our dataset, due to scarcity of data on cancer treatment, we were unable to examine the important question of the predictive value of KRAS mutations in relation to anti-EGFR therapy." (PMID 24885062, 2014). "The paired cancer tissue of 390 samples then served to detect KRAS mutational status by direct sequencing." (PMID 24884535, 2014). "Mutations in the Ras family of small GTPases, particularly KRAS, occur at high frequencies in cancer and represent a major unmet therapeutic need due to the lack of effective targeted therapies." (PMID 25093678, 2014). "Expression of iNOS contributes to the urethane-induced and to genetically, Kirsten rat sarcoma viral oncogene homolog (KRAS) mutation-induced lung carcinogenesis whereas inhibition of iNOS reduced carcinogenesis in animal cancer models." (PMID 24719871, 2014). "The use of MEK inhibitors in patients with KRAS-mutated advanced cancer was associated with higher clinical benefit rates compared to other therapies." (PMID 25313136, 2014). "Oncogenic KRAS mutations are prevalent in virtually all cancer types, making KRAS one of the most frequently mutated genes in human cancers." (PMID 25412182, 2014). "Two malignant tumors, both grade 1, harbored mutations in KRAS and corresponded to the C3/normal-like subtypes and C4/luminal B subtypes, respectively." (PMID 25226589, 2014). "Mutational activation of RAS genes is involved in 33% of human cancers, with mutation of KRAS being the most prevalent (21.6% of human cancers)." (PMID 24583697, 2014). "The alterations are dependent on the presence of KRAS mutations and occur in different types of cancer." (PMID 24368337, 2014). "The KRAS-variant has shown to function as a biomarker for risk of certain cancer types and endometriosis, as well as a predictor for drug response." (PMID 25433809, 2014). "Activating mutations in KRAS are prevalent in cancer, but therapies targeted to oncogenic RAS have been ineffective to date." (PMID 24955217, 2014). "The genotyping of paired synchronous carcinomas indicated that 11 patients (42.3%) exhibited discordant KRAS mutational statuses in terms of the presence of a mutation in only one lesion of the pair or of two different mutations harbored by each lesion." (PMID 24765171, 2014).
cancer (continued). "Compared with male subjects, female subjects are more likely to have KRAS-mutated carcinoma in the transverse colon and descending colon." (PMID 25361007, 2014). "STK33, a relatively understudied protein, has been linked to KRAS mutation-driven cancers and explored as a potential antineoplastic drug target." (PMID 23967198, 2013). "A primary goal of the present study was to design a multiplexed in situ mutation detection assay for point mutations in KRAS, one of the most frequently activated oncogenes in cancer." (PMID 24280411, 2013). "Usually, EGFR mutations are characteristic of tumors in the non-smoker groups of patients, particularly among Asian women, while KRAS mutations are often detected in smoking-associated cancer types." (PMID 23817662, 2013). "In conclusion, we established a sensitive, fast, and cost-effective screening method for KRAS mutations, and successfully detected low-abundance KRAS mutations in clinical samples, which will allow provision of more precise individualized cancer therapy." (PMID 23355875, 2013). "KRAS mutation is one of the most common oncogenic alterations in various human cancers and plays a very important role in multi-step process of cancer development, including cancer initiation, metastasis, and prognosis." (PMID 23355875, 2013). "Within these cancers, 20 T and 22 T possessed KRAS mutations, an association also observed by Yagi in the CIMP-intermediate group." (PMID 23096130, 2013). "KRAS mutations are well known in numerous cancers, located most commonly at exon 2 amino acids G12 and G13, two adjacent amino acids located near the catalytic site, and have been shown to result in constitutive activation of the MAPK signaling pathway." (PMID 24066160, 2013). "After the first detection of KRAS point mutations in the blood plasma of cancer patients in 1994 cfNA have been extensively studied especially with respect to the detection and monitoring of cancers." (PMID 24098698, 2013). "PIK3CA mutation was observed in 105 of 757 (14%) of carcinomas, characterized by location in the proximal colon (54% vs. 34%; P<0.001) and an increased frequency of KRAS mutation (48% vs. 25%; P<0.001)." (PMID 23785428, 2013). "We observed that 5/6 (83%) of low-grade and 1/8 (12.5%) of high-grade MAPK immunopositive carcinomas contained KRAS mutation." (PMID 23388101, 2013). "This was confirmed in vitro, and G12V-mutated cancer cells were resistant to cetuximab, whereas G13D-mutated and KRAS wild-type cancer cells were sensitive." (PMID 22382702, 2012). "Mutations in KRAS occur with the greatest frequency in all human cancers (21.6%), followed by NRAS (8.0%), and HRAS (3.3%)." (PMID 23202889, 2012). "In spite of excluding the patients with a KRAS mutation in their cancer from receiving anti-EGFR therapy, the response rates in the patients with WT KRAS are of the order of 17%–60%." (PMID 23097702, 2012). "A germline microRNA binding site-disrupting variant, the KRAS-variant (rs61764370), is associated with an increased risk of developing several cancers." (PMID 22662244, 2012). "KRAS G12D and G12V mutations are known to be driver mutations in the development of PanINs and preinvasive cancer, as was demonstrated in genetically engineered mouse models." (PMID 23152778, 2012). "The presence of this BRAF mutation was associated with a significantly higher risk of dying from cancer-related causes, independently of other factors such as age, gender, PS, KRAS status, pathological finding, number of metastases, and metastatic sites." (PMID 22043994, 2012). "Of the three human ras isoforms, KRAS is the most frequently altered gene, with mutations occurring in 17%–25% of all cancers." (PMID 23202889, 2012).
cancer (continued). "The KRAS-variant predicts a significant increased risk of developing a third independent cancer in all double primary patients (p<0.01), which was largely due to increased risk for uninformative patients (p<0.005) and also possibly BRCA2 patients (p<0.05)." (PMID 22662244, 2012). "A single nucleotide polymorphism located in the 3'-untranslated region of the KRAS oncogene (KRAS variant; rs61764370) disrupts a let-7 miRNA binding and was recently reported to act as a genetic marker for increased risk of developing human cancers." (PMID 22436609, 2012). "EGFR and KRAS are part of the same signaling pathway, and EGFR overexpression as well as activating KRAS mutations contribute to development and progression of several human cancers, including CRC." (PMID 23173730, 2012). "Overall, this work continues to support the importance of the KRAS-variant broadly in cancer biology, and specifically in women’s health." (PMID 22662244, 2012). "A common target of somatic mutations, especially at codons 12 (82–87%), 13 (13–18%), and 61, KRAS has been implicated in many human cancers." (PMID 22997602, 2012). "Although for some genes mutation hotspots exist (e.g., the KRAS G12, G13, Q61 mutations), the function of most cancer genes can be affected by mutations at different positions." (PMID 22675565, 2012). "In contrast however, the prevalence of the KRAS-variant was significantly enriched in uninformative double primary cancer patients compared to population prevalence (25/92, 27.2%, p<0.001, binomial)." (PMID 22662244, 2012). "This drug has been evaluated in patients with KRAS mutation whose cancer was irinotecan resistant, and the results are yet to be reported." (PMID 23097702, 2012). "The protein product of the normal KRAS gene performs an essential function in normal tissue signaling, and the mutation of a KRAS gene is an essential step in the development of many cancers." (PMID 22537942, 2012). "Nevertheless, our findings should facilitate the rational selection of methods for detecting mutations at the KRAS locus using heterogeneous clinical samples obtained from biopsies of cancer patients." (PMID 22995035, 2012). "KRAS mutations are one of the important events in the tumorigenesis of carcinomas of different organs including the pancreas, colon, and lung." (PMID 23119210, 2012). "The aim of the present study was to determine the frequency of EGFR and KRAS mutations in NSCLC in the West European Dutch population in primary carcinomas and different metastatic locations." (PMID 22528563, 2012). "This would be supported by recent studies which describe a different biological behaviour of carcinomas with KRAS codon 13 compared to other mutations." (PMID 22808230, 2012). "Twenty-seven samples including 8 cell blocks, 9 cytology smears and 10 needle core biopsies, and corresponding 22 resected malignant tumor of lung were correlated for KRAS mutational analysis." (PMID 29147262, 2011). "KRas, one of three Ras isoforms, was used because it is commonly mutated in cancer and is targeted exclusively to the PM, simplifying subsequent analyses." (PMID 21829637, 2011). "Sixty-three MSS/MSI-L cancers showed an almost equal distribution of the wild-type cancers and KRAS-mutated cancers (P = 0.007)." (PMID 21457162, 2011). "The other two cancer cell lines examined in this study (A549 and MiaPaCa2) had KRAS mutations and both were radiosensitized by the MEK inhibitor." (PMID 21411864, 2011). "We retrospectively compared the KRAS mutation detection on cytology specimen or needle core biopsy with corresponding resected malignant neoplasm of lung, the histologic reference standard for mutational analysis." (PMID 29147262, 2011). "Five BRAF mutations and one KRAS c61 mutation were observed among 11 MSI-H cancers when unmatched cases were included (P = 0.007)." (PMID 21457162, 2011).
cancer (continued). "A good example is found in cancer patients who carry a KRAS gene mutation because these patients have been shown to be nonresponsive to anti-HER1 therapeutics." (PMID 22091388, 2011). "Previous studies that have examined the relationship between BRAF and KRAS mutations in a wide range of colonic polyp and cancer tissue have found a mutually exclusive distribution of these mutations." (PMID 21347319, 2011). "Mutations in codon 12 of KRAS are one of the most common mechanisms of activation of ras-related pathways in human cancers." (PMID 21188234, 2011). "Ultra-deep pyrosequencing of KRAS amplicons with GS Junior 454 proved to be a highly sensitive and quantitative technique to analyse somatic mutations in cancer specimens, and which can also be used in a high-throughput assay." (PMID 21943394, 2011). "Concurrent data from the MSI analyses and the KRAS/BRAF mutation analyses were obtained in 74 carcinoma cases." (PMID 21457162, 2011). "With regard to the present prerequisite of KRAS mutation screening before a therapy with Panitumumab and Cetuximab, KRAS is a powerful molecular marker in cancer diagnostics." (PMID 21197450, 2010). "Pre-clinical studies have shown that PI3K pathway activation, through PIK3CA activating mutations or PTEN loss of function, significantly decreases the response of KRAS mutant cancer cells to MEK1/2 inhibitors." (PMID 20149254, 2010). "Activating mutations in RAS genes, most often in KRAS, are found in ~30% of cancers and are generally acquired early in the tumorigenic process." (PMID 20149254, 2010). "Comparison of ALK fusion status with results characterizing the presence of EGFR and KRAS mutations in the same set of cancer samples revealed that ALK fusions occurred in the absence of KRAS mutations." (PMID 20624322, 2010). "Activating KRAS mutations are important for cancer initiation and progression; and have recently been shown to cause primary resistance to therapies targeting the epidermal growth factor receptor." (PMID 21073737, 2010). "We present a novel mechanism whereby cancer cells with oncogenic KRAS mutation, and expressing both HIF-1α and HIF-2α, can maximize ATP production and minimize ROS generation." (PMID 21073737, 2010). "As early as 1991, we reported that KRAS mutations in cancer cell lines frequently demonstrated complete or relative MASI." (PMID 19826477, 2009). "In serous lesions KRAS mutation seems to be a typical feature of borderline tumors and low grade carcinoma." (PMID 19358724, 2009). "We describe here the application of high-resolution melting analysis (HRM) to screen for KRAS mutations in clinical cancer samples." (PMID 17184525, 2006). "This strategy may be extended to other therapeutic agents, where conjugation to Cy5.5-like scaffolds enhances macropinocytic entry into genetically defined cancer cells such as those with KRAS mutations." (PMID 41511990, 2026). "Moreover, our study offers valuable model cell lines for investigating mechanisms underlying replication vulnerability in cancers harbouring oncogenic KRAS mutations." (PMID 41750275, 2026). "RAS family proteins, including HRAS, NRAS, and KRAS, are frequently mutated in cancer." (PMID 41986348, 2026). "While it remains uncertain which strategy will prove most effective, tailored approaches - incorporating immunotherapy and other combinations based on cancer type, tissue origin, KRAS mutations, and downstream effectors – are likely required to achieve durable responses." (PMID 40082410, 2025). "Furthermore, mutant-selective KRAS inhibitors are also expanding as pan-KRAS inhibitors; for instance, KRAS G12C inhibitors are being studied for KRAS G12D-mutated cancers." (PMID 40756996, 2025).
cancer (continued). "Kirsten rat sarcoma viral (KRAS), also known as the P21 gene, is a commonly mutated gene in cancer." (PMID 40308511, 2025). "The KRAS mutation represents the most prevalent oncogenic alteration observed in human cancers." (PMID 41184283, 2025). "This provides a new direction for the immunotherapy of KRAS‐mutated cancers." (PMID 40859900, 2025). "Together, these findings suggest that REGγ is highly expressed in pan-KRAS–mutant tumors and indicate that REGγ may be an independent risk factor or a vulnerability factor in patients with such cancers, potentially impacting malignancy and patient prognosis." (PMID 40091835, 2025). "KRAS mutations are high prevalence oncogenic drivers for multiple cancers." (PMID 40788860, 2025). "This suggests that there are three distinct types of human KRAS mutant cancers, tumors that contain the WT KRAS allele and are heterozygous for KRAS, tumors in which the mutant KRAS allele is exclusively expressed (homozygous), and tumors that have mutant KRAS copy-number gain." (PMID 39412982, 2025). "Elevated ROS levels and DNA fragmentation in cancer cells are also associated with apoptosis and autophagy, indicating that this drug combination can induce apoptosis- or autophagy-mediated cell death in KRAS-mutated PDAC." (PMID 40756996, 2025). "Expectations for significant immunotherapy benefits in KRAS/LKB1 co-mutated cancer patients are tempered, yet LKB1 deficiency may enhance responsiveness to other treatment modalities." (PMID 40611261, 2025). "Furthermore, diminishing the expression of KRAS impedes anabolic pathways, thereby mitigating the metabolic alterations characteristically associated with cancer." (PMID 40390765, 2025). "KRAS is one of the most frequently mutated oncogenes associated with human cancers." (PMID 39400496, 2025). "Interestingly, whilst the spectrum of variants in KRAS/HRAS in human cancer typically involves activating missense variants at codons 12, 13, and 6134, KRAS/HRAS in-frame indels or in-frame duplications have been associated with vascular malformations." (PMID 41350447, 2025). "Similarly, another signaling pathway commonly activated by KRAS mutations and present across multiple cancer types is the PI3K/AKT/mTOR signaling pathway via PI3K and Ras activation by phosphorylation." (PMID 39941724, 2025). "In KRAS-mutant cancers, specific codon mutations differ by tissue type." (PMID 40805153, 2025). "ELI-002 2P, a cancer vaccine targeted against KRAS mutations, showed safe and effective T-cell responses in a phase 1 trial including 25 patients, indicating a reduction in tumor biomarkers and prolonged relapse-free survival in immunotherapy-resistant pancreatic and colorectal tumors." (PMID 40075634, 2025). "Mutations in the GTPase KRAS are responsible for driving nearly 25% of all cancers." (PMID 40762837, 2025). "Finally, it provides the insights into the future prospects for combatting KRAS mutation-associated cancers." (PMID 39820726, 2025). "Oncogenic mutations that render KRAS constitutively active occur frequently in human cancers." (PMID 38328115, 2025). "Additionally, elements such as the immune status of cancer patients and the occurrence of genetic mutations like Kirsten rat sarcoma (KRAS) mutations can also impact their cutaneous toxicity manifestations." (PMID 41377804, 2025). "In addition to overcoming resistance to BRAF inhibitors in melanoma cells and EGFR-tyrosine kinase inhibitor resistance in non–small lung cancer cells, HA15 lowered viability of a wide range of cancer cells, including those bearing various KRAS mutations." (PMID 40699920, 2025). "PPP is reportedly pivotal in the progression and recurrence of cancers with KRAS mutations." (PMID 39970873, 2025).